PDE3B (phosphodiesterase 3B)
Diseases named in the same sentence as PDE3B in open-access papers (continued):
Sharing a sentence is not in itself a finding about the gene and the disease.
Stroke (2 papers, 2010 to 2023). Sudden impairment of blood flow to a part of the brain due to occlusion or rupture of an artery to the brain. "Of these, four (PDE4D, PDE3A, PDE3B, PDE6B) were ranked in the top 1% by the exome method for stroke." (PMID 37492104, 2023).
acute kidney injury (1 paper, 2009). Sudden and sustained deterioration of the kidney function characterized by decreased glomerular filtration rate, increased serum creatinine or oliguria. "Taken together, it is suggested that PDE3B inhibition may have a clinical potential in the treatment of sepsis-induced acute kidney injury." (PMID 19486524, 2009). "Thus attenuation of LPS induced acute kidney injury was likely accomplished by inhibition of PDE3B." (PMID 19486524, 2009).
adrenal hyperplasia (1 paper, 2026). "In primary aldosteronism, recent studies-including data from our group-suggest that germline variants in PDE2A and PDE3B may contribute to bilateral adrenal hyperplasia and autonomous aldosterone production by modulating intracellular cAMP levels." (PMID 41816209, 2026).
cardiomyopathy (1 paper, 2021). A disease of the heart muscle or myocardium proper. "Those authors identified genes implicated in cardiac calcium homeostasis (PDE3B), oxidative stress response (FDXR and SPATA18), and the etiology of cardiomyopathy (SGCD, BBC3 and GDF15)." (PMID 33820914, 2021).
cerebral atherosclerosis (1 paper, 2023). Atherosclerosis of the cerebral vasculature. "Serum circRNA-SCAP and phosphodiesterase 3B (PDE3B) were upregulated in 25 patients with cerebral atherosclerosis, and ox-LDL-disposed THP-1 foam cells, whereas miR-221-5p level was decreased." (PMID 37324939, 2023).
coronary artery disease (1 paper, 2018). "In the gene PDE3B, pLOF variants associate with elevated height, improved body fat distribution and protection from coronary artery disease." (PMID 29691411, 2018). "PDE3B inhibition may be a useful therapeutic strategy to improve body fat distribution and reduce risk of coronary artery disease." (PMID 29691411, 2018).
dermatitis (1 paper, 2019). An inflammatory process affecting the skin. "We found that these mice (in addition to littermates heterozygous for Pde3b germline deletion) remained healthy up to more than 20 weeks of age, with no weight loss, dermatitis, or overt disease, and exhibited restored ex vivo Treg suppressive function." (PMID 30741720, 2019).
injury (1 paper, 2009). Damage inflicted on the body as the direct or indirect result of an external force, with or without disruption of structural continuity. "We only found PDE3B in the kidney, and thus presumably amrinone was inhibiting only PDE3B, suggesting that PDE3B may have a role in endotoxemic kidney injury." (PMID 19486524, 2009).
insulinoma (1 paper, 2025). "In the pancreatic β-cells, cAMP is rapidly degraded by the cyclic 3′, 5′-nucleotide phosphodiesterase 3B (PDE3B), and overexpression of PDE3B in rodent islets or rat insulinoma INS-1 cells decreases insulin secretion in response to glucose and GLP-1." (PMID 40024571, 2025).
leukemia (1 paper, 2025). A malignant (clonal) hematologic disorder, involving hematopoietic stem cells and characterized by the presence of primitive or atypical myeloid or lymphoid cells in the bone marrow and the blood. "We also examined protein expression of SLFN12, PDE3A, and PDE3B in a panel of leukemia cell lines and found that HEL cells exhibit readily detectable amounts of all three proteins." (PMID 41150877, 2025). "To examine this hypothesis, we performed co-immunoprecipitation experiments in U937 cells, a leukemia cell line with undetected PDE3A protein expression but high PDE3B expression." (PMID 41150877, 2025). "Here, we provide evidence that physiologic levels of PDE3B, even in the absence of PDE3A, can be sufficient for heterotetrameric complex formation with SLFN12 to induce velcrin-mediated antineoplastic effects, further demonstrating a potential role for PDE3B in velcrin sensitivity in leukemia." (PMID 41150877, 2025). "We provide evidence that even in less sensitive leukemia cell lines, BAY 2666605 remains effective at relatively low doses and enhances Aza antileukemic effects, suggesting that this combinatorial strategy could be particularly beneficial for patients with lower PDE3A and higher PDE3B expression." (PMID 41150877, 2025).
ovarian carcinoma (1 paper, 2025). A malignant neoplasm originating from the surface ovarian epithelium. "Prior studies have linked PDE3B to metabolic regulation and its dysregulation in cancers such as pancreatic and ovarian cancer." (PMID 40462176, 2025).
Right ventricular hypertrophy (1 paper, 2024). In this case the right ventricle is more muscular than normal, causing a characteristic boot-shaped (coeur-en-sabot) appearance as seen on anterior- posterior chest x-rays. "Although we found that Pde3b knockout mice show elevated trends in RVH and increased RVSP, Pde3a knockout mice exhibit more severe right ventricular hypertrophy, increased RV mass, and significant elevations in RVSP." (PMID 39435735, 2024).
Simpson-Golabi-Behmel syndrome (1 paper, 2019). Simpson-Golabi-Behmel syndrome is a rare X-linked multiple congenital anomalies syndrome, characterized by pre- and postnatal overgrowth, distinctive craniofacial features, variable congenital malformations, organomegaly and an increased tumor risk. "Specifically, the expression and function of PDE3B and GPR151 were evaluated in mouse 3T3-L1 and human Simpson-Golabi-Behmel Syndrome (SGBS) cells, two well-established preadipocyte models used for studying adipocyte differentiation (i.e. adipogenesis) and function." (PMID 31492854, 2019).
squamous cell carcinoma (1 paper, 2013). A carcinoma arising from squamous epithelial cells. "We previously reported that human squamous cell carcinoma (SCC) cell lines refractory to cis-diaminedichloro-platinum II (cisplatin [CDDP]) had significant upregulation of the phosphodiesterase 3B gene (PDE3B), suggesting that inhibiting PDE3B suppresses CDDP resistance." (PMID 24133626, 2013).
steatosis (1 paper, 2025). Increased lipid within the cytoplasm of cells. "For example, the nonselective phosphodiesterase inhibitor pentoxifylline has been shown to reduce steatosis and fibrosis in MASLD patients; this activity may be mediated through PDE3B inhibition." (PMID 40065360, 2025).
tumor (14 papers, 2013 to 2026). "The strong association of PDE3B and HBB with tumor cell proliferation and patient survival underscores their utility as prognostic biomarkers and therapeutic targets." (PMID 40462176, 2025). "Our findings shed light on the molecular mechanisms driving tumor progression and highlight PDE3B and HBB as promising therapeutic targets." (PMID 40462176, 2025). "Both PDE3B and HBB were significantly associated with immune cell infiltration in the tumor microenvironment." (PMID 40462176, 2025). "Upon receiving the SPP1 signal from TAMs via the CD44 receptor, tumor cells activate the integrin and phosphodiesterase 3B (PDE3B) pathways, ultimately inducing chemotherapy resistance." (PMID 41341850, 2025). "This interaction triggers a signaling cascade within the tumor cells, activating the intracellular PDE3B pathway via FYN-mediated integrin signaling." (PMID 39727934, 2024). "We identified a novel subset of macrophages that, through secretion of SPP1, bind to CD44 on tumour cells, activating the PDE3B pathway via the integrin enzyme pathway, thereby inducing chemotherapy resistance in TNBC patients." (PMID 38982317, 2024). "In our present set of tissue samples, differences in DNA methylation levels resulting in differences in the mRNA expression levels of the SPHK1, INHBA, LTB and PDE3B genes were correlated with poorer tumor differentiation." (PMID 36348017, 2023). "Among tumor-related genes characterizing Clusters I and II, differences in the levels of DNA methylation and mRNA expression for the SPHK1, INHBA, LTB and PDE3B genes were correlated with poorer tumor differentiation." (PMID 36348017, 2023). "This may be related to the interaction between secreted SPP1 and CD44 on the surface of tumor cells, which activates the PDE3B pathway." (PMID 41056019, 2026). "Although the effect sizes are relatively small, these results indicate that PDE3B and HBB expression may be linked, albeit modestly, to variations in the tumor immune microenvironment, warranting further investigation." (PMID 40462176, 2025). "Moreover, both genes appear to modulate the tumor immune microenvironment, suggesting that combining PDE3B or HBB inhibition with immune checkpoint blockade may yield synergistic antitumor effects." (PMID 40462176, 2025). "PDE3B and HBB were found to play critical roles in tumor proliferation and immune microenvironment modulation." (PMID 40462176, 2025). "PDE3B is a potent TNBC-promoting agent, and drug antagonism of PDE3B in TNBC can slow tumor growth and prevent metastasis to the lungs." (PMID 39409999, 2024). "Our results suggest that PDE3B and HBB may modulate the immune microenvironment, potentially contributing to tumor immune evasion and progression." (PMID 40462176, 2025). "In non-diabetic women with operable stage I/II breast cancer, short-term neoadjuvant treatment with metformin, although not affecting tumor size, led to decreased Ki67 and phosphodiesterase 3 (PDE3B) staining in postoperative samples." (PMID 39195514, 2024). "Preoperative use of metformin showed no decrease in tumor size but a significant reduction of Ki-67 and PDE3B cells." (PMID 39195514, 2024). "The anti-tumor response to the combination of curcumin and OPCs in mice xenograft tumors and organoids derived from primary human CRC tumors correlated with the altered gene expressions of HSPA5, IHH, PDE3B, cyclin D1 and SEC61B." (PMID 30218018, 2018). "Notably, several upregulated genes, including PDE3B and HBB, overlapped with malignant cell type-specific markers, suggesting these genes may play roles in tumor progression and proliferation." (PMID 40462176, 2025).
cancer (12 papers, 2013 to 2025). A tumor composed of atypical neoplastic, often pleomorphic cells that invade other tissues. "This signal forms a complex with the receptor CD44 on cancer cell surfaces, activating the PDE3B signalling pathway through the integrin enzyme pathway, consequently leading to the resistance of cancer cells to chemotherapy drugs." (PMID 38982317, 2024). "PDE3B activation increases the sensitivity of BLCA cells to copper ionophores, and PDE3B/KRT6B is a potential target for cancer therapy." (PMID 39482784, 2024). "DNMDP is a potent and selective inhibitor of PDE3A and PDE3B, effectively eliminating cancer cells by promoting interactions between PDE3A/B and SFLN12, a critical protein in this process." (PMID 37759695, 2023). "Our results provided novel information on which to base further mechanistic studies of CDDP sensitization by inhibiting PDE3B in human cancer cells and for developing strategies to improve outcomes with concurrent chemotherapy." (PMID 24133626, 2013). "Interestingly, we found five upregulated cancer-related genes (Epha3, Hjurp, Kif26, S1pr3 and Pde3B) that shared miRNAs with the HMGA1P7 transcript." (PMID 25268743, 2014). "Moreover, targeting of PDE3B enhances cisplatin sensitivity in human cancer cells." (PMID 36348017, 2023). "In gastrointestinal stromal tumors, compared to other types of human cancers, PDE3A and PDE3B are highly expressed, offering a promising avenue for targeted therapy." (PMID 37759695, 2023). "This work supported these speculations, because PDE3B expression was associated with CDDP resistance in human cancer cells and also showed that inhibiting the PDE3B gene by gene silencing and cilostazol results in enhanced CDDP responses in various human cancer cell lines in vitro and in vivo." (PMID 24133626, 2013). "Furthermore, the antitumor growth effect of the combination of a PDE3B inhibitor (cilostazol) and CDDP in vivo was also greater than with either cilostazol or CDDP alone, with a significant increase in the number of apoptotic and cell growth-suppressive cancer cells in CDDP-resistance cell lines." (PMID 24133626, 2013).
infection (4 papers, 2010 to 2020). The state of being infected such as from the introduction of a foreign agent such as serum, vaccine, antigenic substance or organism. "To identify the infection of human PDE3A and PDE3B, we observed the altered morphologies of SF9 cells between 48 and 96 h post-infection." (PMID 28959341, 2016).
metabolic disorders (3 papers, 2017 to 2023). "In Pde3b-deficient mice, energy homeostasis regulation is altered, and metabolic disorders occur (including systemic insulin resistance)." (PMID 36675205, 2023).
cardiovascular disease (1 paper, 2022). "Phenotypic follow-up suggests that LoF of PLIN1, PDE3B, and ACVR1C favorably affects metabolic phenotypes (eg, triglycerides [TGs] and high-density lipoprotein [HDL] cholesterol concentrations) and reduces the risk of cardiovascular disease, whereas PLIN4 LoF has adverse health consequences." (PMID 34875679, 2022).
heart disease (1 paper, 2019). "Notably, a recent study identified PDE3B mutations that were associated with elevated blood TG levels and heart disease in humans." (PMID 31105056, 2019).
PDE3B also shares sentences with these, for which no sentence is quoted: Hyperglycemia (3 papers); gastric cancer (2); Hepatic steatosis (2); type 2 diabetes (2); abdominal aortic aneurysm (1); Anorexia (1); anterior ischemic optic neuropathy (1); Arthritis (1); asthma (1); Autoimmunity (1); bladder cancer (1); breast tumors (1); chronic obstructive pulmonary disease (1); depression (1); gastrointestinal stromal tumor (1); glioma (1); hepatocellular carcinoma (1); Hypercholesterolemia (1); infectious disease (1); multiple sclerosis (1); myocarditis (1); myxoma (1); neuroblastoma (1); primary aldosteronism (1); pulmonary arterial hypertension (1); Sepsis (1); testicular cancer (1); viral hepatitis (1).